BAZ2A (bromodomain adjacent to zinc finger domain 2A)
Diseases named in the same sentence as BAZ2A in open-access papers (continued):
Sharing a sentence is not in itself a finding about the gene and the disease.
cancer (13 papers, 2020 to 2025). A tumor composed of atypical neoplastic, often pleomorphic cells that invade other tissues. "Using multiple databases and tissue chip analysis, we explored the pan-cancer expression profile of BAZ2A and its potential association with prognosis and immune invasion in cancer patients." (PMID 38433277, 2024). "Subsequently, we used the TCGA dataset to examine the association between BAZ2A expression and patient outcomes in 21 different cancers." (PMID 38433277, 2024). "Recent studies showed that BAZ2A is also implicated in several cancers such as PCa and hepatocellular carcinoma." (PMID 37184661, 2023). "Taken together, these results point for a role of BAZ2A in the regulation of the expression of genes implicated in cancer-related processes through its TAM domain." (PMID 37184661, 2023). "Studies in mouse non-cancer and differentiated cells showed that the BAZ2A-TAM domain associates with lncRNA pRNA that is required for BAZ2A targeting and silencing of rRNA genes." (PMID 37184661, 2023). "ROC curves were employed to assess the diagnostic utility of BAZ2A across multiple cancer types." (PMID 38433277, 2024). "Our study shows that BAZ2A expression correlates with prognosis and may be a potential diagnostic marker in several cancers." (PMID 38433277, 2024). "The main type of BAZ2A genetic variation in cancer is gene mutation." (PMID 38433277, 2024). "This study aimed to investigate the pan-cancer level expression of BAZ2A and evaluate its prognostic capability, with the aim of identifying cancers in which BAZ2A may function as a diagnostic and prognostic marker." (PMID 38433277, 2024). "The function of BAZ2A in facilitating cancer cell migration was further validated by the detection of epithelial–mesenchymal transition (EMT)-related molecules." (PMID 38433277, 2024). "We found that in a variety of cancers, the increased expression of BAZ2A was found to be correlated with DNA methylation occurring in its promoter region." (PMID 38433277, 2024). "Further investigations with a larger sample size are necessary to more comprehensively assess the expression of BAZ2A in cancer tissues and its potential correlation with various indicators." (PMID 38433277, 2024). "Taken together, BAZ2A gene expression is positively correlated with immune cell infiltration in multiple cancer types." (PMID 38433277, 2024). "Next, we used a timer platform to assess the relationship between BAZ2A gene expression and the degree of immune cell infiltration in 31 cancers." (PMID 38433277, 2024). "BAZ2A is highly expressed in prostate cancer (PCa), and its overexpression predicts cancer occurrence." (PMID 38433277, 2024). "Therefore, we speculate that the role of BAZ2A on tumorigenesis and development is not only regulated by changes in its protein levels but it may also be regulated by mutations and phosphorylation in cancer cells." (PMID 38433277, 2024). "Using the CPTAC dataset, we analyzed the levels of BAZ2A phosphorylation in four cancer types (LIHC, KIRC, OV, and HNSC)." (PMID 38433277, 2024). "The results showed that the expression level of BAZ2A in cancer tissues was higher than that in normal tissues in most cancer species." (PMID 38433277, 2024). "We found that rRNA gene expression in PCa cells is still affected by pRNA and BAZ2A, indicating that PCa cells retain similar mechanisms to establish rRNA gene silencing that were described in non-cancer cells." (PMID 37184661, 2023). "Transwell experiments showed that BAZ2A silencing reduced cancer cell migration and invasion." (PMID 38433277, 2024). "In vitro experiments were performed to assess the function of BAZ2A in cancer cells." (PMID 38433277, 2024). "While PUM1 and BAZ2A have, to our knowledge, not been implicated for the matching cancer types, they have been shown to be potential drivers in other cancers." (PMID 39010058, 2024). "This study explored the expression and mechanism of BAZ2A in tumorigenesis at the pan-cancer level." (PMID 38433277, 2024).
cancer (continued). "We selected LIHC to further explore the function of BAZ2A in cancer." (PMID 38433277, 2024). "While there are many studies on BAZ2A, most of them are focused on its role in a specific cancer." (PMID 38433277, 2024). "This suggests that BAZ2A may be involved in the cancer-related processes by regulating key proteins and molecules involved in these processes." (PMID 38433277, 2024). "CPTAC analysis showed that BAZ2A protein expression was increased in diverse types of cancer." (PMID 38433277, 2024). "Taken together, these observations suggest that BAZ2A may present as a promising therapeutic target for multiple cancer types." (PMID 38433277, 2024). "BAZ2A was shown to promote epigenetic changes in aggressive cancers." (PMID 38433277, 2024). "This further supports the role of BAZ2A in mediating cancer stemness." (PMID 36674511, 2023). "As for BAZ2A, we observed either a positive or negative association with cancer de-differentiation, which seemed to be tumor-specific." (PMID 36674511, 2023). "Previous studies have shown that overexpression of BAZ2A can predict tprostate cancer recurrence." (PMID 36292752, 2022). "The mechanism of BAZ2A in cancer development may involve lipid metabolism." (PMID 38433277, 2024). "Therefore, we chose LIHC to further explore the role of BAZ2A in cancer." (PMID 38433277, 2024). "In most cancers, including LIHC, KIRC, KIRP, PCPG, and HNSC (including HNSC+HPV−, HNSC+HPV+), we observed a positive correlation between BAZ2A mRNA expression and the levels of Tregs and macrophage cell infiltration." (PMID 38433277, 2024). "BAZ1B (also known as WSTF, the component of the WICH complex) and BAZ2A (also known as TIP5, the component of the NRC complex) are relatively well-recognized in cancer-supporting programs." (PMID 36674511, 2023). "Through the analysis of various cancers, we found that the high expression of BAZ2A has significant effects on the survival, prognosis, immune invasion and other aspects of LIHC, while it only has significant effects on some aspects of other cancers." (PMID 38433277, 2024). "To further validate the relationship between BAZ2A and cancer, we performed transcriptome and proteome sequencing in cells silenced for BAZ2A or transfected with NC siRNA as a negative control." (PMID 38433277, 2024). "Therefore, we focused our attention on three genes coding for bromodomain-containing proteins (BAZ2A, BAZ2B, and BRD9) that were all expressed in paclitaxel-resistant SW1736 and 8505C cancer cell lines." (PMID 36983070, 2023).
BAZ2A also shares sentences with these, for which no sentence is quoted: acute myeloid leukemia (1 paper); adenocarcinoma (1); age-related macular degeneration (1); Alzheimer disease (1); anaplastic thyroid carcinoma (1); B-cell acute lymphoblastic leukemia (1); bladder cancer (1); clear cell carcinoma (1); cognitive decline (1); colorectal cancer (1); infection (1); lung carcinoma (1); Lung squamous cell carcinoma (1); myopia (1); nasopharyngeal carcinoma (1); neuroblastoma (1); paraganglioma (1); pheochromocytoma (1); renal carcinoma (1); thyroid tumor (1); triple-negative breast carcinoma (1); tuberculosis (1).